LEFTY2 (left-right determination factor 2)
Description:
Required for left-right (L-R) asymmetry determination of organ systems in mammals. May play a role in endometrial bleeding.
Synonyms: EBAF; LEFTA; LEFTYA; TGFB4
Tractability: Antibody: its Gene Ontology location is reachable by antibodies, with high confidence; UniProt places it where antibodies can reach, with medium confidence; UniProt predicts a signal peptide or a membrane-spanning region.
Gene: Protein-coding gene on chromosome 1 (225,936,598 to 225,941,383, reverse strand). Ensembl gene ENSG00000143768.
Subcellular location: Secreted
Pathways (Reactome):
Developmental Biology: Regulation of signaling by NODAL; Signaling by NODAL
Hemostasis: Platelet degranulation
Gene Ontology:
Molecular function: cytokine activity; growth factor activity; transforming growth factor beta receptor binding
Biological process: anterior/posterior axis specification; BMP signaling pathway
Cellular component: extracellular matrix; extracellular region; platelet alpha granule lumen
Genetic constraint (gnomAD): Loss-of-function variants: 9 observed, 22.33 expected, observed/expected ratio (o/e) 0.4, 90% interval 0.24 to 0.7. The upper end of that interval is the gene's LOEUF score, 0.7, which puts it in group 2 of 6, group 1 being the genes least tolerant of losing a copy. Missense variants: 295 observed, 338.42 expected, observed/expected ratio (o/e) 0.87, 90% interval 0.79 to 0.96. Synonymous variants: 149 observed, 155.38 expected, observed/expected ratio (o/e) 0.96, 90% interval 0.84 to 1.1.
Gene-disease validity (ClinGen):
ClinGen rates the evidence that LEFTY2 causes each of these diseases.
congenital heart disease (autosomal dominant): Disputed. A heart disease that is present at birth.
Homologues: Orthologues: chimpanzee LEFTY2 (100% identical), macaque LEFTY2 (95% identical), pig LEFTY2 (83% identical), mouse Lefty2 (82% identical), mouse Lefty1 (81% identical), rat Lefty1 (81% identical), rat Lefty2 (80% identical), dog LEFTY1 (54% identical), tropical clawed frog lefty1 (37% identical), zebrafish lft2 (35% identical), zebrafish lft1 (34% identical). Paralogues in human: LEFTY1 (96% identical), BMP10 (20% identical), BMP4 (20% identical), BMP2 (20% identical), TGFB1 (20% identical), TGFB2 (19% identical), INHBB (19% identical), GDF2 (19% identical), GDF6 (19% identical), GDF11 (19% identical), TGFB3 (19% identical), GDF1 (18% identical), and 19 more.
Diseases named in the same sentence as LEFTY2 in open-access papers:
LEFTY2 is named in the same sentence as 41 diseases in open-access papers, as found by Europe PMC text mining. Sharing a sentence is not in itself a finding about the gene and the disease. The quoted sentences say what the papers report.
liver fibrosis (5 papers, 2021 to 2024). "Investigating liver fibrosis, a study revealed substantial downregulation of LEFTY2 expression in affected patients." (PMID 38809509, 2024). "Subsequent functional studies elucidated that LEFTY2 mitigates liver fibrosis by suppressing hepatic stellate cell (HSC) activation and collagen synthesis." (PMID 38809509, 2024). "One study showed that circCREBBP inhibits liver fibrosis by binding to has-miR-129/LEFTY2, whereas another revealed that circTUBD1 has been described as a regulator in radiation-induced liver fibrosis through binding to miR-203a-3p/Smad3." (PMID 37217942, 2023). "Furthermore, a recently uncovered pathway involving the circCREBBP-has-miR-1291/LEFTY2 axis was shown to alleviate liver fibrosis." (PMID 38809509, 2024). "However, LEFTY2 alleviates hepatic stellate cell activation and liver fibrosis by inhibiting the TGF-β1/Smad3 pathway." (PMID 36769200, 2023). "In addition, we confirmed that hSA-miRNA-1291 was bound to the 3′UTR of LEFTY2, and the expression of LEFTY2 was decreased and increased in liver fibrosis after the overexpression of circCREBBP." (PMID 34887753, 2021). "In conclusion, our current results reveal a novel mechanism by which circCREBBP alleviates liver fibrosis by targeting the hsa-miR-1291/LEFTY2 axis, and also suggest that circCREBBP may be a potential biomarker for heart failure." (PMID 34887753, 2021). "From the mechanism perspective, CircCREBBP is the sponge for hsa-miR-1291, which up-regulates LEFTY2, thus alleviating liver fibrosis within TGF-β1-treated LX-2 cells, primary HSCs, and liver tissues from CCl4-induced HF mice, and liver fibrosis patients via the hsa-miR-1291/LEFTY2 axis." (PMID 37371520, 2023).
endometrial cancer (4 papers, 2016 to 2024). Primary or metastatic malignant neoplasm involving the endometrium (mucous membrane that lines the endometrial cavity). "Moreover, LEFTY2 has been implicated in the pathogenesis and advancement of endometrial cancer." (PMID 38809509, 2024). "LEFTY2 has been shown to be involved in the progression of a variety of tumors including endometrial cancer." (PMID 32401299, 2020). "LEFTY2 down-regulates Na+/H+ exchanger activity with subsequent inhibition of glycolytic flux and lactate production in endometrial cancer cells." (PMID 32236143, 2020). "We therefore sought to investigate the relationship of LEFTY2 and SGLT1 in endometrial cancer cells." (PMID 32236143, 2020). "LEFTY2 is partially effective by down-regulating Na+/H+ exchanger 1 (NHE-1), leading to a decrease of glycolytic flux (the rate at which molecules proceed through the glycolytic pathway) in endometrial cancer cells." (PMID 32236143, 2020). "In conclusion, the present study demonstrates a novel role of LEFTY2 in up-regulating transcript levels and protein abundance of the Na+ coupled glucose transporter SGLT1, thus stimulating cellular glucose uptake and cellular formation of glycogen in endometrial cancer cells." (PMID 32236143, 2020).
Infertility (3 papers, 2018 to 2025). "Previous studies reported that overexpression of LEFTY2 is associated with unexplained infertility and irregular menstrual bleeding, and in vivo gene transfer studies in mice have also shown inhibition of implantation." (PMID 29230527, 2018). "Our findings provide a novel mechanistic explanation for the clinical observation that elevated LEFTY2 levels are associated with implantation failure and infertility." (PMID 29230527, 2018). "Endometrial LEFTY2 is elevated during the receptive phase in some patients with “unexplained infertility” suggesting that dysregulation of LEFTY2 contributes to infertility." (PMID 29230527, 2018). "A putative candidate is LEFTY2, which we have shown to be involved in unexplained infertility." (PMID 40510743, 2025). "Moreover, patients with ‘unexplained infertility’ have elevated LEFTY2 in the endometrium during the receiving period, indicating that abnormal expression of LEFTY2 results in infertility." (PMID 32401299, 2020).
Alzheimer disease (2 papers, 2025). A progressive, neurodegenerative disease characterized by loss of function and death of nerve cells in several areas of the brain leading to loss of cognitive function such as memory and language. "LEFTY2’s ability to inhibit TGF-β-induced Smad3 phosphorylation offers a potential strategy to modulate the effects of TGF-β in Alzheimer’s disease." (PMID 40244244, 2025). "Furthermore, our findings suggest that LEFTY2 binds to and downregulates APOE4, offering an additional mechanism by which LEFTY2 could benefit Alzheimer’s disease pathology." (PMID 40244244, 2025).
embryonal carcinoma (2 papers, 2014 to 2022). A non-seminomatous malignant germ cell tumor characterized by the presence of large germ cells with abundant cytoplasm resembling epithelial cells, geographic necrosis, high mitotic activity, and pseudoglandular and pseudopapillary structures formation. "The mRNA encoding the Nodal inhibitor Lefty2 is a known activin A-responsive gene, demonstrated in mouse embryonic stem cells and P19 embryonic carcinoma cells, and in human TCam-2 cells." (PMID 35721752, 2022). "However, LEFTY2 is a key factor in various developmental processes and a previous knockdown study from our group reported an up-regulated expression of LEFTY2 after siRNA mediated knockdown of OCT4 or NANOG in the embryonal carcinoma cell line NCCIT." (PMID 25369332, 2014).
glaucoma (2 papers, 2021 to 2023). Increased pressure in the eyeball due to obstruction of the outflow of aqueous humor. "Cluster 2 also differentially expressed glaucoma gene CYP1B1, morphogen-encoding genes LEFTY2, FGF9, and FGF8." (PMID 37665325, 2023). "Interestingly, samples from patients with XFS who had not (yet) developed glaucoma had noticeably less FBN1, LOXL1, and LEFTY2 than samples from patients with XFG." (PMID 34964803, 2021).
ovarian carcinoma (2 papers, 2020 to 2021). A malignant neoplasm originating from the surface ovarian epithelium. "Of note, one of the genes in this signature, LEFTY2, is associated with stemness in ovarian cancer, a known contributor of chemoresistance." (PMID 34729947, 2021).
Arrhythmia (1 paper, 2025). Any cardiac rhythm other than the normal sinus rhythm. "Some of the genetic variants responsible for TSI can also increase the risk for arrhythmias through mutations in genes involved in the Nodal signaling pathway (NODAL and LEFTY2) and in ciliary function (DNAH5)." (PMID 41295344, 2025).
brain tumors (1 paper, 2013). "From these genes of particular interest are HEY2 with a role in notch signaling, LEFTY2 involved in TGFβ-signaling and IGFBP2 which is overexpressed in the stem cell compartment of glioblastomas promoting proliferation and survival of brain tumors." (PMID 24236059, 2013).
congenital heart defects (1 paper, 2021). "Consequently, mice with a deletion in the Lefty2 enhancer that is activated by Nodal display left isomerism while variants in LEFTY1/2 are associated with congenital heart defects." (PMID 33530637, 2021).
COVID-19 (1 paper, 2024). A disease caused by infection with severe acute respiratory syndrome coronavirus 2. "We found 2, 2 and 3 proteins shared between COVID-19 and healthspan/lifespan, such as CXADR and LEFTY2, shared between severe COVID-19 and healthspan/lifespan." (PMID 38575325, 2024). "Notably, we also found LEFTY2 contributes to both COVID-19 and lifespan." (PMID 38575325, 2024). "Two proteins shared between COVID-19 hospitalization and healthspan/lifespan, including CXADR and LEFTY2." (PMID 38575325, 2024).
endometriosis (1 paper, 2022). The growth of functional endometrial tissue in anatomic sites outside the uterine body. "First, the endometrial stromal cells show a relative deficiency of progesterone-sensitive gene markers associated with endometrial stromal cell decidualization in patients with endometriosis (e.g., IGFBP1, LEFTY2, LUM, DCN, etc.)." (PMID 36104692, 2022).
liver diseases (1 paper, 2024). "Recent evidence has increasingly implicated LEFTY2 in liver diseases." (PMID 38809509, 2024).
myocardial infarction (1 paper, 2020). Gross necrosis of the myocardium, as a result of interruption of the blood supply to the area, as in coronary thrombosis. "The dramatic downregulation of THSD4, LEFTY2, and LTBP1 induced by melphalan treatment could collectively enhance the activation of TGF-β signaling pathway and impact the downstream cellular processes such as the induction of apoptosis as observed in myocardial infarction." (PMID 33153480, 2020).
retinal disease (1 paper, 2016). "Several retinal disease-related genes absent in cells transduced with CRX alone were also significantly detected in cells transduced with CRX before NeuroD1 or those transduced with RAX1+CRX before NeuroD1 in a modified medium containing Activin A, Dkk, and Lefty2 or the RPE-conditioned medium." (PMID 27170256, 2016).
testicular teratoma (1 paper, 2023). "The Nodal antagonist Lefty1 and Lefty2 are other possible candidates to continue investigating the impact of microenvironment on testicular teratoma development." (PMID 37180974, 2023).
cancer (8 papers, 2016 to 2025). A tumor composed of atypical neoplastic, often pleomorphic cells that invade other tissues. "Genes often found to be epigenetically silenced or with low expression levels in ovarian or other cancers (Adora1, Bmp3, Ccl6, Ephx2, Lefty2, Pf4, Socs2) were downregulated by MOSE-LTICv in the OFB." (PMID 38264656, 2023). "Accordingly, we found that MSCs showed lower expression of LEFTY2 than iPSCs and cancer cells." (PMID 39621192, 2025). "Additionally, LEFTY1, LEFTY2, and GDF3 showed higher expression in iPSC lines than in cancer cells and MSC lines." (PMID 39621192, 2025). "The left-right determination factor 2 (LEFTY2), considered a suppressor of cell proliferation, tumor growth, and regulator of stem cell properties and embryonic differentiation, seems to be a negative regulator of cancer cell programming." (PMID 29596364, 2018).
tumor (6 papers, 2014 to 2025). "Previously, LEFTY2 was shown to be an inhibitor of cell proliferation and is capable of stimulating apoptosis, thereby counteracting tumor growth." (PMID 32236143, 2020). "LEFTY2 (endometrial bleeding associated factor; EBAF or LEFTYA), a cytokine released shortly before menstrual bleeding, is a negative regulator of cell proliferation and tumour growth." (PMID 32236143, 2020). "LEFTY2 has been described as a TGF-β antagonist and as a tumor supressor." (PMID 32236143, 2020). "Among these genes are ERBB2, CCNA1, FOXC2, LEFTY2, VTN, ACKR3, and PTGS2, which influence processes such as apoptosis, epithelial–mesenchymal transition, angiogenesis, hypoxia responses, and KRAS signaling pathways, all vital for tumor aggressiveness and metastatic spread." (PMID 39000413, 2024). "These genes, including ERBB2, CCNA1, FOXC2, LEFTY2, VTN, ACKR3, and PTGS2, are involved in key processes like apoptosis, epithelial–mesenchymal transition, angiogenesis, response to hypoxia, and KRAS signaling pathways, which are crucial for tumor virulence and the spread of metastases." (PMID 39000413, 2024).
neurodegenerative disease (1 paper, 2025). A disorder of the central nervous system characterized by gradual and progressive loss of neural tissue and neurologic function. "This study reveals for the first time the multifaceted effects of LEFTY2 protein in the co-culture of ADSCs and Ts21 neurons, underscoring its promising therapeutic potential for neuroprotection and neurodegenerative diseases." (PMID 40244244, 2025). "However, LEFTY2’s inability to cross the blood-brain barrier (BBB) presents a significant challenge to its direct application in the treatment of neurodegenerative diseases." (PMID 40244244, 2025).
neurological disorders (1 paper, 2025). "Encapsulation of LEFTY2 within exosomes may facilitate its successful traversal of the BBB, thereby enabling its therapeutic potential in neurological disorders." (PMID 40244244, 2025).
LEFTY2 also shares sentences with these, for which no sentence is quoted: infection (11 papers); Salmonella Infections (2); adenocarcinoma (1); bacterial infection (1); breast carcinoma (1); C. perfringens infection (1); co-infection (1); coccidiosis (1); endometrioid ovarian carcinoma (1); glioblastoma (1); heart failure (1); kidney disease (1); melanoma (1); ovarian tumors (1); ovary (1); placental insufficiency (1); prostate carcinoma (1); pulmonary fibrosis (1); seminoma (1); serous ovarian cancer (1); teratocarcinoma (1).